SNORD114-19 (small nucleolar RNA, C/D box 114-19)
Synonyms: 14q(II-19)
Gene: Small nucleolar RNA gene on chromosome 14 (100,976,477 to 100,976,551, forward strand). Ensembl gene ENSG00000199942.
Gene Ontology:
Biological process: RNA processing
Cellular component: nucleolus
Homologues: Orthologues: chimpanzee SNORD114-19 (100% identical), macaque SNORD114-19 (92% identical). Paralogues in human: SNORD114-12 (81% identical), SNORD114-14 (80% identical), SNORD114-17 (77% identical), SNORD114-3 (76% identical), SNORD114-23 (73% identical), SNORD114-9 (73% identical), SNORD114-21 (72% identical), SNORD114-15 (71% identical), SNORD114-4 (71% identical), SNORD114-11 (69% identical), SNORD114-13 (69% identical), SNORD114-16 (69% identical), and 26 more.